AR (androgen receptor)
Diseases named in the same sentence as AR in open-access papers (continued):
Sharing a sentence is not in itself a finding about the gene and the disease.
colon cancer (36 papers, 2009 to 2024). "Women harbouring two long alleles (≥25 CA repeats) of the ESR2 CA repeat and men having two alleles with ≥23 CAG repeats in AR were at increased risk for colon cancer compared to individuals with shorter alleles of the respective polymorphism." (PMID 25376484, 2014). "Given that the androgen receptor (AR) associates independently with β-Catenin and p68 in PCa cells, and p68 and β-Catenin interact in colon cancer cells." (PMID 23349811, 2013). "Colon tissues are known to express functional nuclear hormone receptors, and specific AR, ERα and ERβ genotypes have been associated with colon cancer." (PMID 19948074, 2009). "However, p68 has been found in the cytoplasm of colon cancer cells where it associates with β-Catenin, and β-Catenin has been shown to interact with the AR in the cytoplasm of PCa cells and move into the nucleus in the presence and absence of androgens." (PMID 23349811, 2013). "The increase of CAG trinucleotide repetitions in the coding sequence of the androgen receptor seems to be related to the lowest trancriptional activation of this receptor resulting in a lower androgenic action on the tissues, increasing the risk of developing colon cancer." (PMID 24720724, 2014). "Another article found that AR and Curcuma aromatica Salisb inhibit colon cancer growth and liver metastasis by regulating Epithelial-mesenchymal transition via the CXCL8/CXCR2 axis and PI3K/AKT/mTOR signaling pathway." (PMID 39215362, 2024). "Colon cancer cells that ectopically expressed AR also repressed β-catenin gene expression upon treatment with DHT, showing that the AR-β-catenin functional interaction can be found in other cellular contexts." (PMID 35372424, 2022). "Androgens signal throughout the body by binding to androgen receptor (AR) expressed in various cell types, including B cells, T cells, neutrophils, and macrophages, as well as colon cancer cell lines." (PMID 33668351, 2021). "In this study, we found that interfering Foxp1 by siRNA reduced the expression of E2F1 and Rb, and promoted the expression of AR and β-catenin, suggesting that Foxp1 is a tumor suppressor gene in colon cancer." (PMID 32951006, 2020). "For instance, as revealed recently, a study demonstrated that AR can attach to regulatory sequence of E-cadherin gene which results in reducing E-cadherin expression and enhancing metastasis in breast and colon cancer cells." (PMID 32153739, 2020). "In colon cancer, it is remarkable that AR is hypermethylated and acts as an interaction hub in the top network." (PMID 24842468, 2014). "Since the membrane androgen receptor, in contrast to the classical intracellular androgen receptor, induces tumor regression in target tissues, we sought to determine the expression and functional status of mAR in colon cancer." (PMID 19948074, 2009). "AR expression in colon cancer cells (in culture) is increased by PGE2 via a cAMP/PKA dependent pathway, an effect therefore mediated through via EP2 or EP4 receptors." (PMID 19558693, 2009). "Furthermore, another article investigated its mechanism of action and found that AR inhibited colon cancer development by inhibiting Wnt5/β-catenin signaling." (PMID 39215362, 2024). "A study suggests that colonic tumor cells could upregulate pro-apoptotic pathways through an AR-dependent mechanism, resulting in tumor regression." (PMID 38023196, 2023). "The PC group showed abundant colonic tumours alongside increased colonic tissue testosterone levels and androgen (AR) and oestrogen (ERα) receptors, whereas E2 and P4 levels with ERβ and progesterone receptor (PGR) decreased significantly compared with the NC group." (PMID 36263327, 2022). "Finally, AR signals are known to have immunosuppressive effects in in-vivo models of various autoimmune diseases, follicular thyroid cancer and colon cancer." (PMID 34736512, 2021). "Activation of AR in colon tumor is known to be a prosurvival signal, and it blocks migration." (PMID 24842468, 2014).
colon cancer (continued). "On the contrary, increasing number of CAG repeats in the androgen receptor was directly associated with colon cancer among men, but not in women." (PMID 19930569, 2009). "An article confirmed the inhibitory effect of AR extract on colon cancer cells MC38 and found that the inhibitory effect showed a correlation with the concentration of AR extract." (PMID 39215362, 2024). "For example, FCX, an arylidene derivative, suppressed the cell growth of AR-selective HCT-8 and HT-29 colon cancer cell lines in higher FCX concentrations." (PMID 38372868, 2024). "Previous studies indicate that AR and TCF4 have overlapping interaction domains on β-catenin and the competitive binding of AR and TCF4 to β-catenin has been shown in both prostate and colon cancer cells." (PMID 26509262, 2015). "Several authors have described AR positivity in almost all samples of both colon tumors and normal mucose [S81, S82], while others have shown smaller, but still significant, percentage of AR positivity (32% colon tumors; 67% non-tumor tissue) [S83]." (PMID 25595907, 2015). "Moreover, E2 and P4 monotherapies equally reduced the numbers of malignant lesions and colonic testosterone levels alongside AR and ERα protein expression, whilst upregulated ERβ and PGR and promoted cell cycle arrest and apoptosis in male mice, as well as in human male colon cancer cell lines." (PMID 36263327, 2022).
apocrine carcinomas (34 papers, 2010 to 2026). "Apocrine carcinomas were intermediate/high grade morphologic variants, with low lymph node ratio and high lymphocytic infiltrate and AR expression, and diagnosed at older age (41.9% at > 70 years)." (PMID 32487046, 2020). "Apocrine carcinoma (AC) of the breast is a rare histological subtype, classically characterized by androgen receptor (AR) positivity with estrogen receptor (ER) and progesterone receptor (PR) negativity." (PMID 41873263, 2026). "AR is expressed variably in histologically distinct subsets of mammary epithelial cells, particularly in apocrine carcinomas and apocrine metaplasia." (PMID 40729351, 2025). "AR reactivity was seen mainly in pure apocrine carcinomas or carcinomas with apocrine or histiocytoid features." (PMID 35444182, 2022). "In apocrine carcinomas, the status of the androgen receptor (AR) and HER-2/neu, which are positive in all and amplified in 30–50%, respectively, is helpful." (PMID 36332545, 2022). "In our previous study of 48 apocrine carcinomas, 1 (2%), 29 (60%), and 35 (73%) were positive for ER-α, AR, and ER-β, respectively." (PMID 34070471, 2021). "Apocrine carcinoma and invasive lobular carcinoma (pleomorphic type) have attracted interest because of their AR positivity." (PMID 34070471, 2021). "The finding is also consistent with the reported presence of an inverse relationship between claudin 4 and androgen receptor expression, as apocrine carcinomas are usually androgen receptor positive." (PMID 31044387, 2020). "Because AR is frequently expressed in apocrine carcinoma and in benign apocrine lesions, we used this marker for differentiating lesions." (PMID 28965222, 2018). "As expected, our LAR samples expressed AR and were histologically consistent with apocrine carcinomas." (PMID 29899867, 2018). "AR is also variably expressed in certain histologically distinct subsets of mammary epithelial cells, including invasive apocrine carcinomas, with molecular apocrine cells uniformly expressing AR but not ER or PR." (PMID 28245550, 2017). "In their study, AR expression was significantly correlated with primary cutaneous apocrine carcinoma (9/9, 100%)." (PMID 27668109, 2016). "Histologically apocrine carcinomas with HR-/AR + profile were GCDFP-15 positive in most cases (27/34, 71.1%, p = 0.039)." (PMID 25070172, 2014). "According to emerging evidence, apocrine carcinomas tend to show estrogen and progesterone receptor negativity and androgen receptor positivity (ER−/PR−/AR+); and expression of Gross cystic disease protein fluid-15 (GCDPF-15)." (PMID 23864975, 2013). "There is strong correlation of AR expression in the apocrine carcinoma subtype, raising the potential for anti-androgen therapy." (PMID 23056620, 2012). "This suggests that AR-positivity is strongly correlated with pure apocrine carcinoma morphology (p<0.0001)." (PMID 23056620, 2012). "Of interest, all of the primary cutaneous apocrine carcinomas (9/9, 100%) and a third of the aggressive digital papillary adenocarcinomas express AR in more than 10% of tumor cells in our current series." (PMID 23056620, 2012). "The other markers showed that typical invasive apocrine carcinomas are AR-positive, ER-negative and EGFR positive." (PMID 20712882, 2010). "Interestingly, apocrine carcinomas, which areER-/PR-/AR+ invasive ductal carcinomas, often show different immune-histo-chemical profiles than other breast cancer subtypes." (PMID 40230896, 2024). "All apocrine carcinomas with known AR status in our cohort were strongly AR-positive." (PMID 36577919, 2022). "All apocrine carcinomas were strongly AR-positive as expected." (PMID 36577919, 2022). "GCDFP-15 is strongly expressed in Apocrine carcinomas which are well known to be AR positive." (PMID 34066838, 2021). "This suggests that AR could promote the development of Apocrine carcinomas in post-menopausal women." (PMID 34066838, 2021).
apocrine carcinomas (continued). "Moreover, some researchers recommend that morphological and IHC criteria (apocrine morphology in >90% of cells together with ER and PR negativity and AR positivity in at least 10% of tumor cell nuclei) should be used to define apocrine carcinoma." (PMID 32697770, 2020). "Anti-androgen therapy may be used in apocrine carcinoma subtype because of strong correlation of AR expression in these type of cancers." (PMID 25815059, 2015). "However, some endocrine-differentiated breastcancers may lack ER and PR expression while still expressing the androgen receptor (AR), as observed in apocrine carcinomas." (PMID 40230896, 2024). "Apocrine carcinomas carry a distinct immunohistochemical profile represented by the negative expression of estrogen receptor (ER) and progesterone receptor (PR), with positive expression of androgen receptor (AR) and gross cystic disease fluid protein-15 (GCDFP-15)." (PMID 34823507, 2021). "We report a case of apocrine carcinoma in a 42-year female with marked adenosis showing apocrine metaplasia and discuss the criteria to diagnose apocrine carcinoma with the emerging concept of androgen receptor positivity with its implication on treatment and management of the patient." (PMID 23864975, 2013). "Forty-three carcinomas were pure apocrine carcinoma (PAC; ER−/AR+), and the remaining 21 were classified as apocrine-like carcinomas (ALCs; ER+/−, AR+/−)." (PMID 37782562, 2024). "Distinguishing apocrine from oncocytic carcinoma relies on immunohistochemistry: apocrine carcinomas are typically ER/PR negative with positive AR and gross cystic disease fluid protein-15 (GCDFP-15) expression." (PMID 41293328, 2025). "In ER-alpha-negative apocrine carcinoma, AR can stimulate cell growth, whereas in luminal ER-alpha-positive BC, AR has an antiproliferative role." (PMID 40729351, 2025). "The term ‘pure apocrine carcinoma’ has been proposed to describe an invasive carcinoma with apocrine morphology that is oestrogen and progesterone receptor negative and androgen receptor positive." (PMID 34537861, 2022). "Almost all intraductal and invasive apocrine carcinomas are positive for GCDFP-15/AR and negative for ER and PgR." (PMID 36553136, 2022). "The term ‘pure apocrine carcinoma’ has been used to define tumours characterised by ER and PR receptor negative status, AR positivity in at least 10% of tumour cell nuclei on IHC and classical apocrine morphology in at least 90% of the tumour." (PMID 34537861, 2022). "Twenty-two of 48 apocrine carcinomas co-expressed AR and ER-β, although expression levels of AR and ER-β were not correlated." (PMID 34070471, 2021). "Both apocrine carcinomas were immunohistochemically negative for estrogen receptor (ER) and progesterone receptor (PgR), but diffusely positive for androgen receptor (AR), GCDFP-15, and HER2." (PMID 25309767, 2014). "Not surprisingly, we further found GCDFP-15 to be elevated in the so-called molecular apocrine carcinomas that are defined by AR expression in the absence of HR expression." (PMID 25070172, 2014). "The Cowden tumors were all AR-positive but only 27% were ER-negative, indicating that the phenotype of apocrine carcinomas is not identical to that of Cowden breast cancers." (PMID 20712882, 2010). "The importance of distinguishing apocrine differentiation is underscored by its potentially favorable prognosis in comparison to other TNBC subtypes.27, ‐29 In the 50 apocrine carcinomas included in this cohort, 92% demonstrated an AR positive, K5 negative or focal, SOX10 negative immunophenotype." (PMID 37306115, 2024). "All apocrine carcinomas were AR-positive, while all non-apocrine tumors were AR-negative." (PMID 27918430, 2016). "The molecular apocrine group is AR positive but ER negative, with an increased androgen signaling and some morphological features of apocrine tumors, lacking, however, the strict criteria for diagnosis of classical apocrine carcinomas." (PMID 25389781, 2014).
apocrine carcinomas (continued). "PIK3CA mutations and PTEN protein expression (IHC) were analyzed in luminal tumors (ER and/or PgR positive), molecular apocrine carcinomas (MAC; ER/PgR negative / AR positive) and hormone receptor (ER/PgR/AR) negative tumors." (PMID 26452060, 2015).
Hypertension (34 papers, 2011 to 2025). The presence of chronic increased pressure in the systemic arterial system. "With respect to AR axis-targeted agents, an increased risk of hypertension was observed across placebo-controlled RCTs." (PMID 38357197, 2024). "The effect of 6β-OHT in mediating Ang II-induced hypertension and associated hypertrophy is dependent on the androgen receptor." (PMID 31948482, 2020). "There is also evidence that androgens and high AR activity can lead to increased smooth-muscle-cell proliferation, which can contribute to thickened arterial walls, further contributing to the risk of hypertension." (PMID 37571268, 2023). "All these findings confirm the pathophysiological role of AR in PCOS-linked hypertension." (PMID 35885010, 2022). "Furthermore, the activity of the AR has been implicated in cardiovascular and respiratory ailments such as vascular ischemia, hypertension, asthma, and cardiac hypertrophy." (PMID 33273918, 2020). "Thus, the finding obtained in this study suggests that individual variations in MR signaling associated with genetic inheritance and comorbidity with hypertension influenced the efficacy of AR-targeting therapeutics." (PMID 30619769, 2018). "Regarding the incidence of stroke, hypertension and atherosclerosis are the main factors that cause stroke, but there is also evidence that endothelial dysfunction can contribute to stroke development, with there being evidence that high levels of AR signaling can lead to endothelial dysfunction." (PMID 37571268, 2023). "The chromosomal locus responsible for the high blood pressure of SHRs is located on the Y chromosome, and its maximum expression depends on testosterone and the androgen receptor." (PMID 40357058, 2025). "Studies in SHRs have shown that testosterone promotes hypertension development via an androgen receptor-mediated mechanism that stimulates the systemic RAS." (PMID 39201324, 2024). "In a recent systematic review and meta-analysis of RCTs that included patients who received AR axis-targeted therapies for nmCRPC, mCRPC, and mHSPC, enzalutamide was ranked the most toxic regarding hypertension in the settings of nmCRPC and mCRPC." (PMID 38357197, 2024). "Investigating the relationship between androgens/AR and hypertension can be beneficial in the future treatment of this and other CVDs." (PMID 37571268, 2023). "As well as hypertension and atherosclerosis, it is also possible that high levels of AR signaling can lead to endothelial dysfunction, another potential risk factor for the development of stroke." (PMID 37571268, 2023). "Androgen receptor inhibitors like spironolactone, eplerenone are having extensive safety profile against hypertension and inhibits aldosterone actions, they also provide possible antiviral and anti-inflammatory actions that reduce lung injuries." (PMID 35517888, 2022). "This review summarizes that, in the vascular smooth muscle, T, via the androgen receptor, reduces the AC expression and increases the α1-AR expression, leading to high BP and hypertension." (PMID 33273918, 2020). "For instance, androgen receptor blockade (flutamide) significantly attenuated the development of hypertension in females and reduced plasma renin activity and rat renin mRNA in the kidney." (PMID 21603136, 2011). "On the other hand, enzalutamide’s direct androgen receptor antagonism, while avoiding mineralocorticoid activation, may still induce hypertension and endothelial dysfunction." (PMID 40805117, 2025). "Furthermore, in SHRs and in the renal wrap model, testosterone has been found to exacerbate hypertension, while flutamide effectively reduces blood pressure, highlighting the AR pathway’s involvement in salt-induced hypertension." (PMID 39201324, 2024).
Hypertension (continued). "Androgen signaling may play a crucial role in this gender disparity, as previous studies have shown that increased androgen receptor (AR) activity and testosterone levels may influence hypertension by altering the renin-angiotensin-aldosterone system." (PMID 38632649, 2024). "For instance, studies on Wistar rats have shown that testosterone supplementation increases blood pressure in both male and female Wistar rats, an effect that can be blocked by the androgen receptor (AR) blocker flutamide, suggesting a direct role of AR in mediating hypertension." (PMID 39201324, 2024). "And lower CAG repeat lengths in the AR coding region are associated with central obesity and hypertension in males rather than females." (PMID 38632649, 2024). "In summary, high AR signaling seemingly worsens hypertension." (PMID 37571268, 2023). "There are multiple mechanisms by which AR activity can have implications on hypertension." (PMID 37571268, 2023). "Regarding hypertension, high AR signaling may have implications on the RAAS, smooth muscle cells, and the SNS." (PMID 37571268, 2023). "This unbalanced ratio of AR to GR/MR activity may play an important role in hypokalemia, sodium retention and hypertension observed with enzalutamide treatment." (PMID 35740293, 2022). "Furthermore, hypertension is positively correlated with AR expression." (PMID 35885010, 2022). "For example, puerarin can have an effect on 45 targets, such as VEGFA, PTGS2, AR, PPARG, and RELA, when treating hypertension." (PMID 32265716, 2020). "It emerged that the main side effect is hypertension, in particular derived from treatment with new hormonal agents, abiraterone and enzalutamide, or new non-steroidal androgen receptor drugs, in particular apalutamide." (PMID 32630204, 2020). "Apart from its actions as a KATP channel opener in the treatment of hypertension and AGA, minoxidil may directly bind to the AR and suppress AR-related functions, including androgen-sensitive LNCaP cell growth." (PMID 24742982, 2014). "In contrast, 5β-DHT is devoid of genomic androgenic activity at the androgen receptor, but is a highly potent and efficacious nongenomic vasodilator in vitro and in vivo and tissue levels of the enzyme that converts TES to 5β-DHT (5β-reductase) are reduced in patients with essential hypertension." (PMID 32843085, 2020).